SESN2 (sestrin 2)
Diseases named in the same sentence as SESN2 in open-access papers (continued):
Sharing a sentence is not in itself a finding about the gene and the disease.
head and neck cancer (5 papers, 2019 to 2025). A primary or metastatic malignant neoplasm affecting the head and neck. "Fisetin, another key flavonoid, induced apoptosis in human head and neck cancer cells via upregulation of sestrin 2 expression and downregulation of phospho-mTOR and myeloid cell leukemia-1 protein." (PMID 34784907, 2021).
pancreatic cancer (5 papers, 2021 to 2025). "This is consistent with a previous study, in pancreatic cancer, where Sesn2 can increase glycolysis and promote the proliferation of pancreatic cancer cells, and both of these pro-tumorigenic effects were reversed by mTOR inhibitors." (PMID 41614860, 2025). "The use of mTOR inhibitors and SESN2 expression vectors in this study clearly demonstrated that SESN2 promotes glycolysis in pancreatic cancer through the mTOR signaling pathway." (PMID 39595578, 2024). "We concluded that EXSOC4 downregulates BIK mRNA and destabilizes SESN2 mRNA in pancreatic cancer cells." (PMID 35008922, 2022). "We showed that EXOSC4 regulates the stability of SESN2 mRNA in pancreatic cancer cells; however, we were unable to evaluate the effects of EXOSC4 on BIK mRNA because of their low expression levels." (PMID 35008922, 2022). "Although EXOSC4 regulates the expression of BIK and SESN2 mRNA in pancreatic cancer cells, how EXOSC4 recognizes the mRNAs is still unclear." (PMID 35008922, 2022). "We concluded that EXOSC4-mediated downregulation of BIK and SESN2 is required for the proliferation of pancreatic cancer cells." (PMID 35008922, 2022). "Our study provides evidence for EXOSC4-mediated regulation of BIK and SESN2 mRNA in the survival of pancreatic tumor cells." (PMID 35008922, 2022). "This latter study indicated that the mTOR signaling pathway participated in sestrin 2-mediated promotion and development of pancreatic cancer." (PMID 34784907, 2021). "In pancreatic cancer, overexpression of sestrin 2 promoted PANC-1 cells proliferation and increased glycolysis, and mTOR inhibitors suppressed these effects in vitro." (PMID 34784907, 2021). "In a separate study, Leu was found to promote the growth and proliferation of pancreatic cancer cells by stimulating the expression of SESN2 and increasing phosphorylated mTOR (p-mTOR), indicating the involvement of the mTOR signaling pathway in pancreatic cancer development." (PMID 39595578, 2024). "Similarly, EXOSC4 has been shown to destabilize SESN2 mRNA, influencing the proliferation of pancreatic cancer cells." (PMID 38164180, 2024). "Furthermore, we revealed that EXOSC4 knockdown induces BIK and SESN2 mRNA levels in pancreatic cancer cells." (PMID 35008922, 2022). "Furthermore, EXOSC4 knockdown increased mRNA levels of BIK and SESN2, which regulate apoptosis in pancreatic cancer cells." (PMID 35008922, 2022). "We speculate that EXOSC4 knockdown leads to the reduction in the growth of pancreatic tumor cells by upregulation of SESN2 and BIK mRNA." (PMID 35008922, 2022). "Additionally, the knockdown of sestrin 2 inhibited the growth of pancreatic cancer in vivo." (PMID 34784907, 2021). "EXOSC4 may degrade SESN2 mRNA levels by regulating EXOSC10 and DIS3 family protein levels in pancreatic cancer cells." (PMID 35008922, 2022). "However, sestrin 2 acts as an oncogene in SCC, pancreatic cancer, and ovarian cancer." (PMID 34784907, 2021).
chronic heart failure (4 papers, 2020 to 2025). "A 36-month follow-up cohort study revealed that SESN2 concentrations in plasma were high in chronic heart failure patients, indicating that the SESN2 increases the incidence of adverse cardiac events." (PMID 39037665, 2025). "Expression of circulating Sesn2 was shown to be increased in aortic dissection and chronic heart failure (CHF) patients." (PMID 32626541, 2020).
Cognitive impairment (4 papers, 2022 to 2024). Abnormal cognition is characterized by deficits in thinking, reasoning, or remembering. "Based on these results, it is reasonable to suspect that cognitive impairment in AD patients may be caused by changes in sestrin-2 associated with two pathologic proteins (Aβ and Tau)." (PMID 38803679, 2024). "Studies have shown that the serum sestrin-2 protein over-expressed significantly in the AD group compared to mild cognitive impairment (MCI) and elderly control groups." (PMID 38803679, 2024). "Another study showed significant overexpression of serum SESN2 protein and mRNA levels in the AD group compared to mild cognitive impairment patients and elderly control groups." (PMID 35195231, 2022). "Surprisingly, a study for AD and mild cognitive impairment patients has suggested that SESN2 plays an important role in the progression of AD." (PMID 36467613, 2022).
Hepatic steatosis (4 papers, 2019 to 2023). Steatosis is a term used to denote lipid accumulation within hepatocytes. "Together, SESN2 confers hepatocyte protection during fatty liver diseases, which is probably associated with regulation on glycolipid metabolism, oxidative stress, ER stress, autophagy, senescence, etc.." (PMID 36841824, 2023). "It is likely that SESN2 deficiency provoked high-fat diet (HFD)-mediated hepatic steatosis, hepatic inflammation, and liver fibrosis." (PMID 31867002, 2019). "Similarly, in a methionine/choline-deficient diet-induced hepatic steatosis model, SESN2 expression could be enhanced in a manner that was dependent on the PERK/eIF2α/ATF4 pathway, and it ameliorated hepatic steatosis progression through autophagy activation." (PMID 31867002, 2019). "Pharmacological induction and genetical reconstitution of SESN2 may be medically favorable for the improvement of fatty liver diseases." (PMID 36841824, 2023).
Hyperglycemia (4 papers, 2019 to 2025). An increased concentration of glucose in the blood. "In summary, we demonstrated that Mg2+ promoted Nrf2 nucleation through SESN2 upregulation, thereby reducing the level of mitochondrial oxidative stress in endothelial cells under hyperglycemia in vitro and promoting peri-implant vascularization and osseointegration in diabetic mice." (PMID 38296940, 2024). "In addition, miR-378a-3p was found to stimulate mitophagy in C2C12 cells exposed to hyperglycemia independently of sestrin-2 (SESN2)." (PMID 33430391, 2021). "However, absence of SESN2 did not completely inhibit the effect of Mg2+ on endothelial cells under hyperglycemia, suggesting other regulatory mechanisms such as ATF4 or SLC7A11 might make an impact." (PMID 38296940, 2024). "Moreover, chronic hyperglycemia results in dysregulated metabolic pathways which might hinder SESN2 from exerting its protective abilities and results in a state where elevated levels of SESN2 do not correspond with effective metabolic regulation." (PMID 39636755, 2025).
Hypertension (4 papers, 2020 to 2025). The presence of chronic increased pressure in the systemic arterial system. "The Sesn2/Nrf2/NOX family axis is a high-profile target in the development of a treatment option for hypertension and warrants further investigation." (PMID 37510117, 2023). "Sesn2, a highly conserved, stress-inducible protein, has the potential to serve as a therapeutic target in treating hypertension." (PMID 37510117, 2023). "Studies show that with Nrf2 deficiency, NOX2 upregulation is observed, linking the potential of the Nrf2/Sesn2 axis to hypertension." (PMID 37510117, 2023). "Further analysis of the interaction between Sesn2 and Ang II is needed to observe the potential advantageous downstream effects of the axis on the pathophysiology of hypertension." (PMID 37510117, 2023). "This review explores potential Sesn2 inducers and activators and how Sesn2 can be incorporated into gene therapy for the treatment of hypertension." (PMID 37510117, 2023). "With insight into the regulatory properties of Sesn2 in these various signaling pathways, we will then discuss how Sesn2 can be utilized as a treatment option for hypertension." (PMID 37510117, 2023). "Proper management of the overactive Ang II exhibited in hypertension by Sesn2 can lead to a decrease in the ROS produced by NADPH oxidase." (PMID 37510117, 2023). "Further exploration is needed on the antioxidant properties and signaling pathway interactions of Sesn2 in hypertension." (PMID 37510117, 2023). "Sesn2 possesses antioxidant properties and can interact with various signaling pathways involved in hypertension." (PMID 37510117, 2023). "The details mentioned in this review indicate the potential of Sesn2 as a therapeutic target for hypertension." (PMID 37510117, 2023). "These unique properties can combat the etiology of hypertension, making Sesn2 an excellent target in the development of therapeutic treatment plans for hypertension." (PMID 37510117, 2023). "This study is aimed at investigating the level of circulating Sesn1, Sesn2, and Sesn3 in hypertension patients." (PMID 32626541, 2020). "The results of our study revealed that Sesn1, Sesn2, and Sesn3 levels were significantly increased in hypertension patients when compared with the normotensive subjects." (PMID 32626541, 2020). "In conclusion, we found that plasma Sesn1, Sesn2, and Sesn3 levels were increased in hypertension patients and positively correlated to the blood pressure values." (PMID 32626541, 2020). "Nondipper hypertension patients exhibited higher plasma Sesn1, Sesn2, and Sesn3 levels when compared to dipper hypertension patients." (PMID 32626541, 2020). "In the present study, the plasma levels of the antioxidant proteins Sesn1, Sesn2, and Sesn3 in hypertension patients were detected." (PMID 32626541, 2020). "Newly discovered findings could give rise to the development of a highly specific and effective treatment protocol involving Sesn2 to ameliorate the effects of hypertension." (PMID 37510117, 2023). "Sesn2 can be utilized in a multitude of ways as a therapeutic modality in hypertension." (PMID 37510117, 2023). "Lastly, adeno-associated virus (AAV) vectors, an effective method for gene therapy delivery, could be utilized to favorably manipulate Sesn2 in hypertension." (PMID 37510117, 2023). "The use of the vectors could potentially increase Sesn2 expression to counteract the high amount of ROS production/oxidative stress exhibited in hypertension." (PMID 37510117, 2023). "Lastly, we will intricately link the etiology of hypertension to how Sesn2 could potentially serve as a target in the treatment of hypertension." (PMID 37510117, 2023). "The Nrf2/Sesn2 pathway could lead to a viable early treatment modality for hypertension and warrants further examination." (PMID 37510117, 2023).
Hypertension (continued). "This review describes the major processes contributing to the development of hypertension and how Sestrin2 (Sesn2), an antioxidative protein, could be a potential target in the treatment of hypertension." (PMID 37510117, 2023). "Sesn2, a highly conserved, stress-inducible protein, has the structural and functional characteristics to be a potential therapeutic target to alleviate the progression of hypertension." (PMID 37510117, 2023). "Therefore, this study is aimed at examining plasma Sesn1, Sesn2, and Sesn3 levels in hypertension patients." (PMID 32626541, 2020). "Further, AMPK activation by Sesn2 can influence overactive NOX4, decreasing the ROS production exhibited in hypertension." (PMID 37510117, 2023). "Continuing, we will further discuss in this review the axiomatic relationships of various signaling pathways of Sesn2, including nuclear factor erythroid 2-related factor 2 (Nrf2), AMPK/mTORC, and Ang II in relation to hypertension." (PMID 37510117, 2023). "Compared with the normotensive subjects, Sesn1, Sesn2, and Sesn3 levels were increased in patients with hypertension, with a gradual increase between the groups with grade I, grade II, and grade III hypertension." (PMID 32626541, 2020). "Furthermore, plasma Sesn1, Sesn2, and Sesn3 levels were positively correlated to both SBP and DBP in hypertension patients." (PMID 32626541, 2020). "The development of a high-specificity Nrf2 agonist could activate Sesn2 in non-oxidative or low-oxidative stress conditions, such as early or pre-hypertension." (PMID 37510117, 2023). "Moreover, Sesn1, Sesn2, and Sesn3 levels were elevated in patients with dipper hypertension and further increased in patients with nondipper hypertension." (PMID 32626541, 2020).
ischemia (4 papers, 2015 to 2023). A hypoperfusion of the BLOOD through an organ or tissue caused by a PATHOLOGIC CONSTRICTION or obstruction of its BLOOD VESSELS, or an absence of BLOOD CIRCULATION. "During ischemia, SESN2 protein expression was found to be increased in the adult cardiomyocytes just after 5 minutes, indicating decreased degradation of the protein instead of increased de novo synthesis." (PMID 36902310, 2023). "SESN2 silencing by SESN2-specific siRNA duplexes exacerbated neuronal damage and increased infarct volume in response to ischemia modeled by the occlusion and reperfusion of the middle cerebral artery." (PMID 36902310, 2023). "Moreover, elevated Sesn2 inhibited IR-induced mTOR signalling and sensitized MCF7 cells to IR irradiation, in contrast, the expression of Sesn2 protected ischemia, low glucose and H2O2 induced apoptosis in LNCaP cells." (PMID 25962159, 2015).
metabolic syndrome (4 papers, 2023 to 2025). A cluster of metabolic risk factors for CARDIOVASCULAR DISEASES and TYPE 2 DIABETES MELLITUS. "As a matter of fact, studies that found an increase in serum sestrin 2 in individuals with metabolic syndrome, as in this study, explained this paradoxical increase as a compensatory mechanism to overcome metabolic stress." (PMID 38813505, 2023). "The current study aims to assess serum SESN2 levels in treatment-naive women with PCOS and compare them to healthy controls, exploring its potential as a stress-responsive protein and a biomarker in the pathophysiology of this metabolic syndrome." (PMID 40225432, 2025).
myocardial infarct (4 papers, 2017 to 2023). "Furthermore, in a model of myocardial infarction, SESN2 is up-regulated in both pro-inflammatory M1 and anti-inflammatory M2 type cardiac macrophages, and SESN2 suppresses inflammatory response of M1 macrophages via inhibiting mTORC1 signaling and enhances M2 type macrophage polarization." (PMID 36841824, 2023).
acute kidney injury (3 papers, 2019 to 2025). Sudden and sustained deterioration of the kidney function characterized by decreased glomerular filtration rate, increased serum creatinine or oliguria. "Recently, the role of SESN2 in the protection of renal tubules during acute kidney injury (AKI) has been explored." (PMID 31205582, 2019). "Previous research demonstrated that treatment of acute kidney injury (AKI) with the antioxidant S-PPE NP reduced the levels of the oxidative stress-responsive protein Sestrin2 (SESN2), and suggested that kidney injury molecule 1 (KIM-1) could serve as a biomarker for early tubular injury." (PMID 40485171, 2025).
Aortic dissection (3 papers, 2019 to 2022). Aortic dissection refers to a tear in the intimal layer of the aorta causing a separation between the intima and the medial layers of the aorta. "In another study of human aortic dissection, plasma Sesn2 levels were found to be positively correlated with MDA levels and negatively correlated with SOD levels." (PMID 32626541, 2020). "As reported, SESN2 levels were elevated in patients with chronic heart failure, coronary artery diseases, aortic dissection, and atrial fibrillation." (PMID 31867002, 2019). "Similarly, SESN2 attenuated Ang II-induced apoptosis of SMCs via regulating the Nrf2 pathway and decreased the occurrence of aortic dissection." (PMID 31867002, 2019). "Moreover, upregulation of SESN2 decreased Ang II-induced SMC apoptosis and attenuated the occurrence and progression of aortic dissection." (PMID 31867002, 2019).
asthma (3 papers, 2020 to 2025). "Kang et al79 demonstrated that patients with asthma had a significantly higher plasma SESN2 level than the control group." (PMID 33942488, 2021). "The only positive finding from the current study was the increased levels of Sestrin 2 in both sputum supernatant and cell pellet in patients with severe asthma." (PMID 32050426, 2020). "Sestrin 2 levels significantly differed in favor of severe asthma in both sputum supernatant and cell pellet." (PMID 32050426, 2020). "The positive finding refers to Sestrin 2, which was increased in both sputum supernatant and cell pellet in patients with severe asthma." (PMID 32050426, 2020). "Although the underlying mechanism for the significant upregulation of SESN2 has not been determined in patients with OSA and asthma, SESN2 might be a promising biomarker for OSA and asthma." (PMID 33942488, 2021). "In this study, we demonstrated that Sestrin 2 levels were higher in both sputum supernatant and cell pellet of patients with severe asthma compared to those with milder forms of the disease, whereas neither Endocan nor SIRT1 serum levels differed between patients with different asthma severity." (PMID 32050426, 2020).
Atrophy (3 papers, 2021 to 2024). Any weakening or degeneration, especially through lack of use. "Early experiments confirmed that knocking down Sesn2 in a denervation-induced atrophy model accelerates the progression of skeletal muscle atrophy and is induced by the conversion of slow-twitch to fast-twitch myofibers." (PMID 39117956, 2024). "Altogether, the present study reveals an endogenous protection factor—SESN2 against denervation-induced muscle atrophy." (PMID 34429398, 2021). "Given that the progression of muscle atrophy occurred mainly in the first 14 days in a coincidental manner, we speculated that SESN2 might participate in the process of muscle atrophy." (PMID 35945510, 2022).